ABCB9 (ATP binding cassette subfamily B member 9)
Description:
ATP-dependent low-affinity peptide transporter which translocates a broad spectrum of peptides from the cytosol to the lysosomal lumen for degradation. Displays a broad peptide length specificity from 6-mer up to at least 59-mer peptides with an optimum of 23-mers. Binds and transports smaller and larger peptides with the same affinity. Favors positively charged, aromatic or hydrophobic residues in the N- and C-terminal positions whereas negatively charged residues as well as asparagine and methionine are not favored.
Synonyms: TAPL; EST122234
Tractability: Antibody: UniProt predicts a signal peptide or a membrane-spanning region. PROTAC: ubiquitination databases record sites on it; its protein half-life has been measured.
Target class: ATP-binding cassette; ABCB subfamily; Transporter; Primary active transporter
Gene: Protein-coding gene on chromosome 12 (122,920,951 to 122,981,649, reverse strand). Ensembl gene ENSG00000150967.
Subcellular location: Lysosome membrane
Subcellular location (Human Protein Atlas): Vesicles
Pathways (Reactome):
Transport of small molecules: ABC-family protein mediated transport
Gene Ontology:
Molecular function: ABC-type oligopeptide transporter activity; ABC-type peptide transporter activity; ATP binding; protein binding; protein homodimerization activity; transmembrane transporter activity; ABC-type transporter activity; ATP hydrolysis activity
Biological process: antigen processing and presentation of peptide antigen via MHC class I; peptide metabolic process; peptide transport; oligopeptide transmembrane transport; transmembrane transport
Cellular component: early endosome; endoplasmic reticulum; endoplasmic reticulum membrane; lysosomal membrane; lysosome; membrane
Genetic constraint (gnomAD): Loss-of-function variants: 36 observed, 59.76 expected, observed/expected ratio (o/e) 0.6, 90% interval 0.46 to 0.8. The upper end of that interval is the gene's LOEUF score, 0.8, which puts it in group 3 of 6, group 1 being the genes least tolerant of losing a copy. Missense variants: 943 observed, 1,039.1 expected, observed/expected ratio (o/e) 0.91, 90% interval 0.86 to 0.96. Synonymous variants: 435 observed, 450.81 expected, observed/expected ratio (o/e) 0.96, 90% interval 0.89 to 1.04.
Homologues: Orthologues: chimpanzee ABCB9 (100% identical), macaque ABCB9 (99% identical), mouse Abcb9 (94% identical), rat Abcb9 (94% identical), dog ABCB9 (93% identical), pig ABCB9 (93% identical), guinea pig ABCB9 (89% identical), rabbit ABCB9 (84% identical), tropical clawed frog abcb9 (62% identical), zebrafish abcb9 (54% identical), Caenorhabditis elegans haf-9 (40% identical). Paralogues in human: TAP2 (36% identical), TAP1 (35% identical), ABCB1 (31% identical), ABCB10 (31% identical), ABCB11 (30% identical), ABCB4 (30% identical), ABCB8 (30% identical), ABCB5 (28% identical), ABCB6 (23% identical), ABCB7 (22% identical).
Diseases named in the same sentence as ABCB9 in open-access papers:
ABCB9 is named in the same sentence as 25 diseases in open-access papers, as found by Europe PMC text mining. Sharing a sentence is not in itself a finding about the gene and the disease. The quoted sentences say what the papers report.
non-small cell lung carcinoma (3 papers, 2015 to 2022). A group of at least three distinct histological types of lung cancer, including non-small cell squamous cell carcinoma, adenocarcinoma, and large cell carcinoma. "In non-small cell lung cancer, miR-31 was also shown to exert anti-apoptotic properties by inhibiting ABCB9, a gene known to play a role in drug resistance." (PMID 25706292, 2015). "ABCB9, located on 12q24.31, is an antigen processing-like (TAPL) transporter that has been found to be involved in the development and progression of various malignant tumors, such as ovarian cancer and non-small cell lung cancer." (PMID 35903355, 2022).
ovarian carcinoma (3 papers, 2021 to 2022). A malignant neoplasm originating from the surface ovarian epithelium. "It has been demonstrated that the expression of ABCB9 is lower in colorectal and ovarian tumors than normal tissues and is associated with poor survival of ovarian cancer." (PMID 34944632, 2021). "Importantly, low expression of ABCB9 is associated with poor survival of ovarian cancer patients." (PMID 35563053, 2022).
type 2 diabetes (3 papers, 2015 to 2019). "Other notable candidate genes with loss of H3K27me3 occupancy are ABCB9 (associated with type 2 diabetes); Sts (associated with HF diet and ob/ob models of obesity and type 2 diabetes); and Ucn2 (associated with heart failure patients)." (PMID 28425976, 2017). "We confirmed associations with type 2 diabetes for five of the seven SNPs (TMEM154-rs6813195, FAF1-rs17106184, POU5F1/TCF19-rs3130501, ARL15-rs702634 and ABCB9/MPHOSPH9-rs4275659)." (PMID 25799151, 2015). "A trans-ethnic meta-analysis of type 2 diabetes genome-wide association studies has identified seven novel susceptibility variants in or near TMEM154, SSR1/RREB1, FAF1, POU5F1/TCF19, LPP, ARL15 and ABCB9/MPHOSPH9." (PMID 25799151, 2015).
bladder cancer (2 papers, 2022 to 2023). "The high expression of ABCB9, SPTBN2, GULP1, IGF1, P4HB, NES and DPYSL2 and the low expression of ANXA6, OAS1, RAD9a, DNASE2B and FANCF would be beneficial to the prognosis of bladder cancer patients." (PMID 37845668, 2023).
chorioamnionitis (2 papers, 2018 to 2020). A morphologic finding indicating inflammation of the fetal sac membranes. "Up-regulation of ABCB9 mRNA was also detected in chorioamnionitis (p < 0.05)." (PMID 32042278, 2020). "Up-regulation of ABCB9, ABCC2 and ABCF2 mRNA was detected in chorioamnionitis (p<0.05), whereas placental ABCB1 (P-gp; p=0.051) and ABCG2 (breast cancer resistance protein-BCRP) mRNA levels (p=0.055) approached near significant up-regulation." (PMID 29402780, 2018). "ABCB9, ABCC2 and ABCF2 were also up-regulated by chorioamnionitis though very little is known concerning the potential function of these transporters in the placenta." (PMID 29402780, 2018).
hepatocellular carcinoma (2 papers, 2019 to 2021). A malignant tumor that arises from hepatocytes. "However, based on previous studies, several researchers found some evidence that certain genes may predispose patients to liver or ICP disease, such as ABCB9 associated with hepatocellular carcinoma and ABCG2 associated with ICP." (PMID 33546617, 2021). "Concerning hsa-miRNA-31-5p, only few studies have addressed how increased expression contributes to chemoresistance: in malignant pleural mesothelioma and hepatocellular carcinoma, it promotes chemoresistance by targeting OCT1 and ABCB9." (PMID 31467538, 2019).
glioma (1 paper, 2025). A benign or malignant brain and spinal cord tumor that arises from glial cells (astrocytes, oligodendrocytes, ependymal cells). "SVs identified in the Mastiffs clade intersected with the introns of three genes: ABCB9, PITPNM2, and DENR, that last of which was found to have two intronic deletions and has been implicated in canine glioma susceptibility." (PMID 40971676, 2025).
leiomyoma (1 paper, 2022). A well-circumscribed benign smooth muscle neoplasm characterized by the presence of spindle cells with cigar-shaped nuclei, interlacing fascicles, and a whorled pattern. "Since progesterone is a major promoter of leiomyoma development and growth, the role of ABCB9 in fibroids in general, and its function in progesterone-driven growth of leiomyomas in particular, needs further exploration." (PMID 35903355, 2022).
malaria (1 paper, 2019). Malaria is a serious and sometimes fatal disease caused by a parasite that commonly infects a certain type of mosquito which feeds on humans. "Placental Abcb9 mRNA expression was also downregulated in malaria-infected mice; however, whether this decrease is related to malarial infection that leads to PTD, remains to be determined; its location in the placental barrier is unknown." (PMID 31391498, 2019).
cancer (4 papers, 2022 to 2025). A tumor composed of atypical neoplastic, often pleomorphic cells that invade other tissues. "ABCB9 is a member of the ATP-binding cassette subfamily B. The ATP-binding cassette family, as membrane drug transporters, participates in the development of drug resistance in a variety of tumors by allowing anticancer drugs to flow out of cancer cells." (PMID 37845668, 2023). "Using the datasets in The Cancer Genome Atlas and Gene Expression Omnibus, we found upregulated ABC transporters that either negatively impacted survival in univariate analyses (ABCA1, ABCA13, ABCB9, ABCD4) or were independent negative prognosis factors for patients with GBM (ABCA13, ABCB9)." (PMID 39861164, 2025).
tumor (4 papers, 2016 to 2023). "The genetic variant rs2270788 in ABCB9 was found to be associated with both the risk and tumor size of ULs in African American participants." (PMID 35903355, 2022). "miR-31 also regulates the expression of several target-suppressive or oncogenic genes, such as ARID1A, SATB2, EMSY, and ABCB9, to affect tumorigenesis and tumor progression and prognosis." (PMID 27793031, 2016). "Interestingly, of the few genes that, via sPLS-DA, were predicted to contribute to tumor regression at certain stage-to-stage interfaces—including DAPK2, PLAC9, ABCB9, MELTF, CTHRC1, and OCIAD2, testing for LUAD patient survivability via AK4 combination resulted in a negative prognosis." (PMID 34940617, 2021). "Statistical analysis performed with the U Mann–Whitney test showed a statistically significantly higher expression level of the ABCB9 (p = 0.000), ABCC1 (p = 0.009), and ABCC6 (p = 0.000) genes in patients without tumor cell invasion into fat tissue." (PMID 36674773, 2023). "The average expression level of the ABCA3 (p = 0.007), ABCB9 (p = 0.000), ABCC1 (p = 0.000), ABCC4 (p = 0.000), ABCC5 (p = 0.000), and ABCC6 (p = 0.000) genes was statistically significantly higher in patients without tumor cell infiltration in the lymph vessels." (PMID 36674773, 2023).
infection (2 papers, 2015 to 2018). The state of being infected such as from the introduction of a foreign agent such as serum, vaccine, antigenic substance or organism. "A role for ABCB9 has been proposed at the blood-testes barrier and in T lymphocytes in response to infection." (PMID 29402780, 2018). "Up-regulated levels of ABCB9 and MCP1 during infection help the host to mobilize immune cells and present antigen against H. contortus infection." (PMID 25903558, 2015).
ABCB9 also shares sentences with these, for which no sentence is quoted: heart failure (2 papers); amyotrophic lateral sclerosis (1); frontotemporal lobar degeneration (1); inflammatory bowel disease (1); major depression (1); malignant pleural mesothelioma (1); Obesity (1); ovarian tumors (1); psoriasis (1); rheumatoid arthritis (1); schizophrenia (1); synucleinopathy (1); vascular dementia (1).